U3 (Small nucleolar RNA U3 )
Synonyms: LOC124904152
Gene: Small nucleolar RNA gene on chromosome 17 (44,025,020 to 44,025,223, reverse strand). Ensembl gene ENSG00000221044.
Gene Ontology:
Biological process: RNA processing
Cellular component: nucleolus
Homologues: Orthologues: chimpanzee U3 (99% identical), macaque U3 (93% identical), rat LOC120095489 (76% identical), rat U3 (76% identical), mouse Gm24826 (74% identical), dog U3 (40% identical). Paralogues in human: U3 (79% identical), U3 (78% identical), U3 (77% identical), U3 (75% identical), SNORD3G (75% identical), SNORD3P1 (75% identical), U3 (74% identical), SNORD3D (74% identical), SNORD3H (74% identical), SNORD3E (73% identical), U3 (73% identical), U3 (72% identical), and 12 more.